INS (insulin)
Diseases named in the same sentence as INS in open-access papers (continued):
Sharing a sentence is not in itself a finding about the gene and the disease.
type 2 diabetes (continued). "These alterations precede any observable weight gain but could contribute to the mechanisms of impaired insulin signaling, which could ultimately lead to the development of type 2 diabetes, as well as other metabolic disorders." (PMID 31024337, 2019). "Traditionally, gender differences in metabolism (mechanisms of accumulation of adipose tissue and mobilization of fat reserves, homeostasis of glucose, secretion, and effects of insulin) and related diseases (MetS and type 1 and type 2 diabetes) are explained by the effects of sex hormones." (PMID 31671663, 2019). "This pattern of results was seen using both IVW MR and MR Egger approaches and is entirely consistent with both the Developmental Overnutrition and Fetal Insulin Hypotheses models of the relationship between type 2 diabetes and birthweight." (PMID 30815700, 2019). "Type 2 diabetes is characterized on the one hand by deficiency in insulin secretion and on the other hand by insulin resistance (the insulin produced does not satisfactorily act on the target organs)." (PMID 30744021, 2019). "Here the authors set out to characterize changes in beta-cell metabolism in hyperglycemia which may contribute to insufficient insulin secretion in type 2 diabetes and, using a multi-omics approach, find that mitochondrial metabolism is perturbed." (PMID 31171772, 2019). "GPR40 is a pharmacological target to increase insulin secretion in type 2 diabetes, and a synthetic ligand TAK-872 has been shown to induce a β-arrestin-biased pathway instead of G protein signals that are typically elicited by native ligands such as palmitate and oleate." (PMID 31354618, 2019). "Owing to a limited number of genetic instruments, of the original five genetically correlated psychiatric phenotypes we were able to test only schizophrenia and major depressive disorder, in addition to the metabolic phenotypes BMI, insulin secretion and type 2 diabetes." (PMID 30696823, 2019). "In obesity or type 2 diabetes (T2D), proximal insulin signaling is often impaired." (PMID 31127081, 2019). "Sphingolipid metabolism generates metabolites related to type 2 diabetes and insulin action." (PMID 31293078, 2019). "In addition, as demonstrated in studies evaluating the results of intensification of insulin therapy in people with type 2 diabetes, the basal-bolus regimen provides a small further improvement in HbA1c levels compared to simpler insulin delivery regimens." (PMID 30871141, 2019). "Impaired beta-cell insulin secretion is a key pathological feature of type 2 diabetes." (PMID 31346174, 2019). "Glucose metabolism is mainly detected when insulin resistance mechanism is performed, while we focus on vascular lesions, so nevertheless, further experiments are required to validate their effects in type 2 diabetes." (PMID 31179340, 2019). "Indeed, the main clinical phenotypes associated with metabolic disorders, taking admixture into account, are related to type 2 diabetes, insulin secretion, body mass index, obesity, and adiposity." (PMID 31554886, 2019). "Most of our knowledge about the pathogenic factors involved in DCM has been provided by studies performed in a variety of rodent models of type 1 and type 2 diabetes or genetically engineered mouse models that lack important molecular components of the insulin signaling pathway." (PMID 31212580, 2019). "The data behind the hypothesis were drawn from a study in which GLP-1 had been infused intravenously to subjects with type 1 or type 2 diabetes during meal ingestion together with a variable insulin infusion to maintain glucose at euglycemic levels." (PMID 31275243, 2019). "Only in the case of men with type 2 diabetes subjected to a 6-month insulin mix therapy, plasma omentin-1 concentrations were significantly higher as compared to the observed concentration in the same men before implementation of the therapy as well as in the men from the control group." (PMID 31195747, 2019).
type 2 diabetes (continued). "Some people with type 1 diabetes may also be prescribed metformin, particularly if overweight or obese or insulin resistant, and may have been included in this dataset if their records indicated an erroneous diagnosis of type 2 diabetes." (PMID 30777033, 2019). "In a retrospective cohort analysis using the UK Clinical Practice Research Datalink (CPRD), we assessed the outcome of 55,530 patients with type 2 diabetes starting their second or third non-insulin glucose-lowering medication, with a baseline HbA1c > 58 mmol/mol (7.5%)." (PMID 30979373, 2019). "Also, fasting serum FA levels correlated well with the impaired insulin secretion in type 2 diabetes patients." (PMID 30450940, 2019). "In older patients with type 2 diabetes, acarbose may also increase insulin sensitivity; its contraindications include inflammatory bowel disease and liver cirrhosis." (PMID 31781665, 2019). "First degree relatives to patients with type 2 diabetes have a markedly increased risk of developing type 2 diabetes and are more insulin resistant than subjects with no family history of type 2 diabetes." (PMID 31133864, 2019). "Long-term complications of diabetes may arise in both type 1 and type 2 diabetes and in both insulin-treated and non-insulin-treated DM individuals." (PMID 31565656, 2019). "Compared with the similar analysis based on the whole disease network, the analysis based on those closely associated with T2D displayed more specific and striking enriched issues with T2D (such as type II diabetes mellitus, insulin signaling pathway, and glucose metabolic process)." (PMID 30972105, 2019). "DM is characterized by hyperglycaemia as a consequence of impaired insulin secretion (as experienced in type 1 diabetes) or insulin resistance (as experienced in type 2 diabetes) resulting in diabetic complications such as diabetic retinopathy, neuropathy, and nephropathy." (PMID 31662777, 2019). "This nationwide population-based nested case-control study has demonstrated an intensified effect of chronic viral hepatitis on premixed insulin analogues for HCC development among newly diagnosed type 2 diabetes patients ever prescribed any antidiabetic agents." (PMID 31200528, 2019). "A pharmacological elevation of GLP-1 is able to restore insulin secretion in type 2 diabetes." (PMID 31275246, 2019). "When B cells were congenitally deficient, HFD-fed obese mice did not develop type 2 diabetes, their fasting sugar, and insulin tolerance tests were unaffected, but helper CD4 T cell function was ameliorated." (PMID 31998318, 2019). "It was difficult to enroll additional subjects because this trial was strictly for patients with poorly controlled type 2 diabetes, and these patients could receive insulin injection as a standard treatment." (PMID 31415655, 2019). "Here, we cultured three different insulin pathway signaling compromised flies (heteroallelic mutant combinations, akin to diabetes mellitus type II) and wild type control flies, for the extent of one generation in different isocaloric diets fed at libitum, with or without extra methionine added." (PMID 30805360, 2019). "In turn, the obtained results of omentin-1 in patients with type 2 diabetes after treatment with insulin were higher in relation to the values of plasma protein concentration before the implementation of therapy, as well as in comparison with people with metabolically healthy obesity." (PMID 31195747, 2019). "Currently, the main diagnostic markers of type 2 diabetes mellitus used in clinical practice are related to measurements of impaired glucose metabolism, but these markers do not reveal disturbances in insulin sensitivity in different tissues." (PMID 31920980, 2019). "Reduced insulin sensitivity as well as reduced insulin secretion are culprits in type 2 diabetes." (PMID 32010143, 2019).
type 2 diabetes (continued). "While rat models do not directly recapitulate the progression of type 2 diabetes in humans, studies within similar metabolic conditions (hyperglycemia, insulin resistance) can provide needed insight into the skeletal muscle mitochondrial function in type 2 diabetes." (PMID 31652915, 2019). "Recently, a case report showed that planned intermittent fasting may help to reverse type 2 diabetes and eliminate the need for insulin treatment." (PMID 30642126, 2019). "Although, type-2 diabetes have been considered to be associated with metabolic syndrome, the ability of the islets to lose insulin production cannot be ruled out." (PMID 31191312, 2019). "The secretion of glucagon is complex and involves a combination of various factors; defective suppression of glucagon by glucose or insulin and especially insulin resistance in α-cells have been suggested as potential mechanisms for the hyperglucagonemia in type 2 diabetes." (PMID 31546230, 2019). "However, despite the focus on HbA1c and glycemic control, intensive efforts to lower glucose and HbA1c by artificially elevating insulin above the existing hyperinsulinemia common to type 2 diabetes result in an increase in mortality." (PMID 31485454, 2019). "It is possible that the effects of resistance training on the glycogen synthase pathway are dependent on pre-training glucose tolerance and/or insulin sensitivity given that improvements in glycogen synthase activity in type 2 diabetics were nearly double that of healthy controls." (PMID 31684154, 2019). "In animal studies, feeding millet improved insulin sensitivity and blood lipid metabolism in type 2 diabetic mice, it was expected that millet might be beneficial to the prevention of type 2 diabetes." (PMID 30875961, 2019). "Early studies in humans have shown that insulin-stimulated vasodilation could be a significant contributor to insulin-stimulated glucose uptake by a mechanism involving eNOS, which can be impaired in people with obesity or type 2 diabetes." (PMID 30754657, 2019). "Inadequate insulin secretion in type-2 diabetes (T2D) is treated clinically by two main strategies." (PMID 31099751, 2019). "Such patients have early manifestations of insufficient insulin secretion and may be clinically misdiagnosed with type I or atypical type II diabetes." (PMID 31322178, 2019). "Use of insulin for type 2 diabetes treatment was more common in migrants." (PMID 31673340, 2019). "In type 2 diabetes, glucagon dysregulation is as important as insulin dysregulation." (PMID 31357734, 2019). "EPA improves insulin sensitivity and blood sugar in patients with type 2 diabetes." (PMID 31557807, 2019). "This may precipitate decreased insulin-sensitivity and subsequently type 2 diabetes mellitus (T2DM) and coronary artery disease (CAD)." (PMID 31890043, 2019). "The majority (93.6%) had type 2 diabetes, and 53.8% were on insulin." (PMID 30606164, 2019). "Frequent and potentially fatal complications may occur among hypoglycemic patients with type 1 or type II diabetes treated with insulin, and in patients with type II diabetes treated with certain oral anti-diabetic medicines." (PMID 31652253, 2019). "Eighteen BAM and 15 WEM with type 2 diabetes underwent a two-stage hyperinsulinaemic–euglycaemic clamp with stable glucose and glycerol isotope tracers to assess tissue-specific insulin sensitivity and a magnetic resonance imaging scan to assess body composition." (PMID 30729259, 2019). "Major causes of type 2 diabetes are a lack of insulin or insulin resistance, both of which cause high blood sugar." (PMID 31709055, 2019). "Type-2 diabetes mellitus (T2DM) is a disorder of the metabolism of sugar, fat and protein caused by insulin resistance (IR) or the relative insufficiency of insulin secretion in islet beta cells, in which its occurrence and development are impacted by the dual factors of environment and heredity." (PMID 33817136, 2019).
type 2 diabetes (continued). "In the T2D dataset, DMGs identified by RADAR were enriched in related pathways including insulin signaling pathways, type II diabetes mellitus, mTOR pathways, and AKT pathways, indicating a role that m6A might play in T2D." (PMID 31870409, 2019). "The next obvious question then clearly was if exercise training could reverse the insulin-resistant state in individuals with type 2 diabetes." (PMID 30730811, 2019). "Excess SFAs (by dietary or conversion of sugars into saturated fats by lipogenesis) results in rigid cellular membranes that in turn impair insulin signaling, glucose uptake, and blood circulation, making a malignant cycle that contributes to the development of obvious type 2 diabetes." (PMID 31030467, 2019). "In addition, in HFD mice, type 2 diabetes occurs when β-cells in the pancreas fail to secrete sufficient amounts of insulin to meet the metabolic demand." (PMID 31731426, 2019). "Many individuals with type 2 diabetes may require mealtime bolus insulin dosing in addition to basal insulin." (PMID 30871141, 2019). "Patients only receiving insulin were thereby excluded, which might have resulted in the elimination of some patients with advanced type 2 diabetes." (PMID 31730627, 2019). "Furthermore, several GWAS SNPs influence traits that are reported to be rapidly evolving, such as type 2 diabetes, body mass index, modified Stumvoll insulin sensitivity index, and obesity-related traits." (PMID 30930929, 2019). "A recent study looking at amino acid concentration in 5181 non‐diabetic men aged between 45 and 73 years from the Finnish town Kuopio in relation with the development of type 2 diabetes found that a high L‐serine concentration is correlated to improved insulin secretion and sensitivity." (PMID 31344283, 2019). "Interestingly peroxisome proliferator-activated receptor γ (PPARγ) agonist are insulin sensitizers and widely used in the treatment of type 2 diabetes and cardiac hypertrophy has been reported in few preclinical studies using such agonists." (PMID 31340810, 2019). "In patients with type II diabetes, which is characterized by the inability of tissues to detect insulin-sensitivity, the process of gluconeogenesis is increased in the liver where glucose uptake and its conversion in insulin-sensitive tissues are severely impaired." (PMID 31311548, 2019). "Previous studies have shown that enlarged, hypertrophic adipocytes are less responsive to insulin, and that adipocyte size could serve as a predictor for the development of type 2 diabetes." (PMID 31506540, 2019). "Therefore, we planned to study the effect of saroglitazar on insulin sensitivity in patients with type 2 diabetes mellitus (T2DM) with hypertriglyceridemia by hyperinsulinemic-euglycemic clamp." (PMID 31831868, 2019). "Researches have shown that the LKB1–AMPK–GLUT4 signaling pathway could have abnormal expression in the skeletal muscle of patients with type 2 diabetes, consequently reducing the insulin sensitivity and increasing the blood glucose level." (PMID 31890042, 2019). "However, the fat sand rat model is so peculiar that it has little relevance to human type 2 diabetes, especially given that decompensated diabetic humans would probably be treated with exogenous insulin." (PMID 31406105, 2019). "Obese patients with type 2 diabetes are more likely to need insulin, which may explain the differences in the relative increases in the use of antidiabetic agents between the Netherlands and the US." (PMID 30901377, 2019). "Type II diabetes mellitus is a chronic metabolic disease characterized by persistent hyperglycemia because of a progressive condition in which the body becomes resistant to the typical effects of insulin or loses the ability to produce insulin." (PMID 31618207, 2019). "Holloszy subsequently proposed that exercise training might increase insulin sensitivity and responsiveness assessed with these newer and more valid methods in type 2 diabetes." (PMID 30730811, 2019).
type 2 diabetes (continued). "Indeed, brown and beige adipose tissues have been demonstrated to play a role in glucose homeostasis, insulin sensitivity, and lipid metabolism—all factors related to pathogenesis of type 2 diabetes." (PMID 30506389, 2019). "For example, impaired insulin sensitivity is a fundamental characteristic of Type 2 diabetes." (PMID 31263701, 2019). "Moreover, it was demonstrated that omentin enhances insulin sensitivity and that omentin protects against obesity and its comorbidities such as Type 2 diabetes (T2D) and CVDs." (PMID 31174318, 2019). "In addition, the serum ucOC concentrations were shown to correlate with the insulin sensitivity in patients with type 2 diabetes." (PMID 31050684, 2019). "Additionally, eating competence was associated with a lower prevalence of previously undiagnosed type 2 diabetes, abdominal obesity, metabolic syndrome and hypertriglyceridaemia, and with better insulin sensitivity (p < 0.05 for all)." (PMID 31905938, 2019). "In addition to the main drugs delivery was injection way of insulin, the other was used oral way for all kinds of type 2 diabetes drugs, so it was also called oral medications." (PMID 31072232, 2019). "In humans, silymarin has been described to ameliorate glycemic control, with a reduction in both fasting insulin and exogenous insulin requirements in insulin‐treated patients with type 2 diabetes and hepatic cirrhosis (Voroneanu, Nistor, Dumea, Apetrii, & Covic, 2016)." (PMID 30632209, 2019). "NLRP3 inflammasomes have also been reported to be involved in low-grade subclinical inflammation induced by chronic exposure to high levels of free fatty acids and glucose, leading to increased apoptosis and impaired insulin secretion of β-cells in obese type 2 diabetes mellitus (T2D) patients." (PMID 31182982, 2019). "In turn, LZ-8 may play an important role in type 2 diabetes, reducing lymphocyte infiltration and increasing insulin detection by insulin in beta cells and lowering plasma glucose in non-obese diabetic mice." (PMID 31717970, 2019). "Mechanistic studies have shown that RBP4 may be involved in several etiologic pathways leading to type 2 diabetes development, such as dysregulation of insulin resistance and insulin secretion, inflammation, and failure of intracellular lipid homeostasis." (PMID 30651745, 2019). "However, this treatment is effective only in those people with type 2 diabetes who have preserved endogenous insulin secretion." (PMID 30871141, 2019). "In the reviewRegulating the beta cell mass as a strategy for type-2diabetes treatment, L.Song and co-authors indicate that modern antidiabetic therapy, which is mainlyaimed at increasing the secretion and efficacy of insulin as well as at glucoseuptake, is symptomatic." (PMID 31024748, 2019). "Weight loss and improved beta-cell function both contribute to maintenance of long-term glycemic control in patients with type 2 diabetes, and increased glucose stimulated insulin secretion may contribute to postprandial hypoglycemia in NGT subjects." (PMID 31641146, 2019). "In type II diabetes mellitus, insulin secretion, integration of energy metabolism pathways, KCNJ11, and ABCC8 were the common targets, which may be regulated by XSN." (PMID 31607935, 2019). "Hepatic steatosis, an early stage of non-alcoholic fatty liver disease, is commonly present in obesity and type 2 diabetes, and is associated with reduced hepatic omega-3 polyunsaturated fatty acid (n3-PUFA) status that impacts on the anti-inflammatory and insulin sensitizing functions of n3-PUFA." (PMID 31022865, 2019). "Two studies found that PKCθ muscle protein content was increased in patients with type 2 diabetes and this implies that insulin signalling could be attenuated through activation by DAG." (PMID 30871020, 2019). "It is also suggested that C-peptide may have a suppressive effect on insulin action in type 2 diabetes." (PMID 31731426, 2019).